PLD2 (phospholipase D2)
Diseases named in the same sentence as PLD2 in open-access papers (continued):
Sharing a sentence is not in itself a finding about the gene and the disease.
cancer (48 papers, 2010 to 2026). A tumor composed of atypical neoplastic, often pleomorphic cells that invade other tissues. "PLD1 and PLD2 are implicated in cancer by activating pathways central to tumor growth, cell cycle progression and angiogenesis." (PMID 40259095, 2025). "PLD1 and PLD2 are overexpressed in various cancers and are intimately associated with tumorigenesis via the generation of PA13." (PMID 34471223, 2021). "The Phospholipase D (PLD) superfamily is linked to neurological disease, cancer, and fertility, and a recent report correlated a potential loss-of-function PLD2 polymorphism with hypotension." (PMID 28831159, 2017). "PLD2 has been linked to a plethora of cellular functions such as cell signaling, membrane remodeling and cancer." (PMID 26492088, 2015). "Elevated PLD2 activity has been implicated in increased protease secretion, a hallmark of invasive cancer cells." (PMID 27713341, 2010). "Furthermore, the canonical PLD isoforms (PLD1 and PLD2) are well known to be implicated in cancer by activating oncogenic pathways." (PMID 40259095, 2025). "Phospholipase D2 (PLD2) plays critical roles in cellular signaling, membrane dynamics, and cancer progression." (PMID 41223946, 2025). "Specifically, OA's ability to disrupt PLD2’s lipid raft association and enhance its colocalization with PIP2 clusters appears to underlie its potent regulatory role in cancer cell signaling and migration." (PMID 41223946, 2025). "This unique dual functionality positions PLD2 as a key player in cytoskeletal reorganization and cancer metastasis." (PMID 41223946, 2025). "Background and Objectives: PLD2 has been identified as playing a critical role in cancer cell motility and migration and other pathophysiological processes." (PMID 38706911, 2024). "PLD2 has also emerged as a target for cancer and other diseases, and VU0364739 has served as a proof-of-concept compound." (PMID 38945955, 2024). "Although the roles of PLD1 and PLD2 in cancer cells have been well studied, their functions in the tumor microenvironment have not yet been clarified." (PMID 36131027, 2022). "Other top genes overlapping with significant CpGs include PLD2 (cancer development and progression), and TGFB2 (regulation of angiogenesis and heart development)." (PMID 36457128, 2022). "PLD2 is a regulator of the Syndecan-Syntenin-Alix pathway for exosome biogenesis and acts as an oncogene in several cancer types." (PMID 36320056, 2022). "Taken together, these results suggest that SAH-induced PLD2 upregulation increases the threshold for cancer cells to undergo apoptotic cell death." (PMID 32998768, 2020). "We found that growth of tumors formed by subcutaneously transplanted cancer cells is enhanced in Pld2-knockout mice." (PMID 29674728, 2018). "The number of CD8+ T cells, which induce cancer cell death, significantly decreased in the tumor produced in Pld2-knockout mice." (PMID 29674728, 2018). "Since CD8+ T cells eliminate various types of cancer, it is of interest to examine progression of other types of cancer in Pld2-deleted mice." (PMID 29674728, 2018). "A high level of PLD2 is found in colorectal and breast cancers, implying its possible role in cancer invasion and metastasis." (PMID 28533957, 2017). "Elevated PLD2 expression is known to be a cancer survival signal, but how PLD2 regulates other signaling proteins or how it is regulated at the level of gene expression is not well characterized." (PMID 28011629, 2017). "Not only the cytoskeleton reorganization function is reported in the physiologic cell processes; many researches also mention PLD2 involvement in the metastasis of cancer." (PMID 28533957, 2017). "First and foremost, cancer cell lines have increased levels of PLD2 and therefore higher levels of PA production." (PMID 28011629, 2017).
cancer (continued). "Conversely, silencing the PLD2 gene in cancer cells or implanting mice with micro-osmotic (Alzet) pumps containing the PLD small-molecule inhibitors FIPI and VU0155072-2 resulted in smaller tumors and fewer lung metastases." (PMID 27851813, 2016). "Over-expression of catalytically inactive PLD2 in normal endothelial and cancer cells inhibited cell migration, suggesting a role for PLD in regulation of cell motility." (PMID 23667561, 2013). "Over-expression of catalytically inactive PLD2 inhibited migration of ECs, fibroblasts and cancer cells suggesting a role for PLD2/PA signaling in regulation of cell motility." (PMID 23667561, 2013). "In the present study, Wnt3a and mimicking of Wnt signaling through LiCl and BIO resulted in induction of both PLD1 and PLD2 in a variety of cancer cells." (PMID 20711340, 2010). "Considering the fact that there are highly complex interactions among a variety of cancer-relevant pathways, PLD2 may act as a potentially promising prognostic marker or therapeutic target and be applied to prevention and treatment of advanced CRC." (PMID 38706911, 2024). "The expression of PLD2 is elevated in several cancer types, and here, using public patient databases and our cohort of patients, we show that this is also the case in OC in which it may be related to decreased OS." (PMID 38403587, 2024). "Also, extracellular vesicles, which can be secreted by cancer cells, are enriched in PA and phospholipase D2, which produces PA." (PMID 37509443, 2023). "Moreover, increased expression of PLD enzymes (PLD1 and PLD2) has been implicated as contributing factors in several types of human cancer, and the role of PLD in pathways involved in cancer progression and tumorigenesis has been reported." (PMID 36791913, 2023). "Other factors such as LAPTM4B and PLD2 are overexpressed in a variety of cancers and promote cancer proliferation, invasion and metastasis; yet it is not known whether and how they exert cancer progression activities within the exosomal pathway." (PMID 36320056, 2022). "The interaction between PLD2 and Sirt1 is required for protection of cancer cells from apoptosis." (PMID 34471223, 2021). "In addition, the PLD2-PX domain directly binds to and activates PKCζ, which is critical for the survival of cancer cells." (PMID 34471223, 2021). "It has been reported that inhibition of PLD2 has therapeutic potential against cancers." (PMID 32998768, 2020). "However, combination of rapamycin or temozolomide, anti-cancer drugs, with PLD2 inhibitor exerted synergistic effects in increasing apoptosis." (PMID 32998768, 2020). "Since inhibition of Treg cell function strongly suppresses tumor progression, clarification of the PLD2 involvement in the function of Treg cells might provide insight into anti-cancer immunotherapies." (PMID 29674728, 2018). "In conclusion, we report here a regulatory relationship between PARN and PLD2/PA, which constitutes a new and possibly essential component in post-transcriptional regulation in higher eukaryotes, as well as in disease states such as cancer." (PMID 28011629, 2017). "Cancer cells having low levels of RNase could potentially maintain a more active pool of RNA and facilitate overexpression of proteins like PLD2 that are highly relevant to cell migration and metastasis." (PMID 28011629, 2017). "Elevated PLD2 activity has been found in various cancers including breast, colon, and kidney." (PMID 27713341, 2010). "In addition to the enzymatic activity of PLD, PLD1- or PLD2-specific binding proteins and the modulation of other regulatory factors may affect distinct cancer signaling pathways mediated by PLD isozymes." (PMID 38945955, 2024). "Although the effect of combination of HDAC inhibitor with PLD2 inhibitor looks like to be accumulative, the accumulative effects can in fact result in a potential advantage for the potential use of this double treatment in cancer, increasing the spectrum of the targeted pathways." (PMID 32998768, 2020).
cancer (continued). "We further investigated whether SAHA and/or PLD2 inhibition affect apoptosis of the cancer cells." (PMID 32998768, 2020). "A review of the literature on PC metabolism in various cancers revealed that FADS1, FASN, PCYT1A, LPCAT1, and PLD2 are involved in PC metabolism in multiple cancers." (PMID 40148316, 2025). "Among the differentially expressed genes, we found that several genes related to cancer progression (HMGA2, PLD2, MMP9, GLI1, GLI2, SLUG and MDR1) were expressed at a low level after knocking out APN." (PMID 32457292, 2020). "In terms of major cancer-related proteins among SM-specific hubs, NOTCH1, ARFGEF1, PLD2, and RPTOR were strongly aligned with hallmarks of NSCLC." (PMID 29062084, 2017). "As illustrated in the results section, three interconnected proteins, ARFGEF1, PLD2, and RPTOR, were successively activated, stimulating the cancer driver mTOR SP." (PMID 29062084, 2017). "Elevation of either PLD1 or PLD2 (the two mammalian isoforms of PLD) is able to transform fibroblasts and contribute to cancer progression." (PMID 24103483, 2014). "Besides lactate, cancer cells are also predicted to release prostaglandin D in the TME, which is consistent with the Phospholipase D2 (PLD2) overexpression and secretion by CRC cells." (PMID 36557249, 2022). "Since the expression of PLD2 and SIRT1 is upregulated in various cancers, the interaction between proteins may be increased in cancers and contribute to antiapoptotic function." (PMID 34471223, 2021). "PLD2 protein expression was generally higher in PCa cells derived from Gleason-scored cancer biopsy samples than from a tissue sample defined as non-tumorigenic." (PMID 31673104, 2019). "PLD2 protein was generally detected as punctate perinuclear dots (white arrows) in the cytoplasm of BPH1, LNCaP and PC3 prostate epithelial cell lines as well as in one cancer cell preparation (H702) purified from GS7 biopsy tissue." (PMID 31673104, 2019). "In the present study, we provide evidence that PLD2 positively regulates proliferation of CD8+ T cells, which have a critical function in cancer cell elimination, through TCR-dependent activation of the Ras-Erk signaling pathway, thereby contributing to the suppression of tumor progression." (PMID 29674728, 2018). "PLD2, EGFR and JAK3 were involved in common pathways that maximize cancer cell invasion." (PMID 28399876, 2017). "Melanoma cell lines, but not primary melanocytes, have high levels of PLD activity that is dependent on PKC, Rho and phorbol ester, suggesting that it is PLD1 rather than PLD2 that is involved in cancer progression." (PMID 24103483, 2014). "This review will introduce the classical mammalian PLD’s, PLD1 and PLD2, followed by the mechanisms of intracellular regulation and a status of the scientific literature in the crucial involvement of PLD in cancer, mostly through its role in cell migration, invasion and metastasis." (PMID 24103483, 2014). "By positioning PLD2 S-acylation at the intersection of lipid metabolism and actin remodeling, our study highlights a mechanism that may be exploited therapeutically in TNBC and other cancers with dysregulated lipid signaling." (PMID 41223946, 2025). "If PLD2 confers redundancy by generating PA in the absence of PLD1, PLD2-derived PA may mediate the regulation of cancer signaling by PLD1." (PMID 38945955, 2024). "However, unlike PLD2, PLD1 has been well studied for its ability to regulate Wnt/β-catenin and its associated cancer signaling pathways in addition to affecting cancer stemness." (PMID 38945955, 2024). "In mammalian cells, phospholipase D2 (PLD2) localizes at rims of Golgi complex and regulates the constitutive secretion in epithelial cells and glycoconjugate trafficking in mast cells, thus involves in plethora of cellular functions including cell signaling, apoptosis and cancer." (PMID 34879072, 2021).
cancer (continued). "Moreover, only PLD1 in the tumor microenvironment, but not PLD2, promoted tumor growth and metastasis; whereas, cell-intrinsic roles for PLD2 to accelerate cancer cells migration and invasion have been widely accepted." (PMID 28399876, 2017). "Hence, these findings suggest the potential use of PLD inhibitors, especially dual inhibitor of PLD1 and PLD2, such as FIPI, may ultimately provide the most utility for cancer therapy." (PMID 28399876, 2017). "We also present evidence that PLD2/PA regulates PARN expression and that PARN also in turn regulates PLD2 transcript levels in a negative feedback loop that is deregulated in cancer cells." (PMID 28011629, 2017). "Since PLD2 levels are naturally high in cancer cells, our results indicate that either PARN is deregulated in cancer cells, not allowing inhibition of PLD2 expression, or that PLD2 activity contributes to increased mRNA stabilization, or both." (PMID 28011629, 2017).
tumor (28 papers, 2010 to 2025). "Phospholipase D (PLD), especially its isoforms PLD1 and PLD2, is implicated in tumor malignancy, GSC maintenance, and resistance to therapies." (PMID 40565099, 2025). "We have reported that stable overexpression of either PLD1 or PLD2 in fibroblasts causes transformation and enhancement of tumor formation." (PMID 20711340, 2010). "In addition to multiple single mutation events, we located two parallel single mutations (CHD3 and PLD2), which evolved independently in adenomatous polyps and in tumour cells." (PMID 36451239, 2022). "Altogether, these data indicate that PLD2, whose expression is induced by hypoxia, is an important oncogene in OC and that its overexpression leads to increased tumor stemness." (PMID 38403587, 2024). "Together, these results indicated that lower PLD2 expression enhanced tumor invasion in vitro, which played a pivotal role during CRC progression." (PMID 38706911, 2024). "We found that the increased tumor growth provoked by PLD2 overexpression was reduced upon treatment with PLDi." (PMID 38403587, 2024). "Impaired CD8+ T-cell infiltration into the tumor microenvironment in Pld2−/− mice promotes tumor growth." (PMID 36131027, 2022). "Studies have shown that PLD2 secreted by tumor cells promotes tumor development by changing the microenvironment." (PMID 35836256, 2022). "The expression level of multiple genes associated with tumor growth, such as STAT3, PDGFA, PLD2, and PIK3R2, showed a significant decrease." (PMID 35291563, 2022). "PLD2 mRNA was upregulated in CRC tumours, and primary fibroblasts cultured in media used to grow PLD2-overexpressing CRC cells showed increased senescence." (PMID 35954376, 2022). "That tumor-induced neovascularization was significantly suppressed by treatment with PLD2 inhibitor or SAHA." (PMID 32998768, 2020). "In genetically engineered mouse models, PLD1 can modulate tumor progression and similar effects have been reported for PLD2." (PMID 31231646, 2019). "Tumor growth in WT mice transplanted with Pld2−/− bone marrow cells (rWTdKO) was promoted compared with that in rWTdWT." (PMID 29674728, 2018). "Number of CD8+ T cells, but not that of CD4+ T cells, in the tumor formed in Pld2−/− mice was lower than that in the tumor in WT mice, which was confirmed with Pld2−/−/Cas9 mice." (PMID 29674728, 2018). "When these T cells in the thymus and spleen were analyzed by flow cytometry, there was no obvious difference in the population of CD4+ and CD8+ thymocytes between WT and Pld2−/− tumor-bearing mice." (PMID 29674728, 2018). "This is supported by the results that Pld2−/− mice reconstituted with WT bone marrow cells (rKOdWT) tended to slightly augment tumor growth compared with rWTdWT." (PMID 29674728, 2018). "From the unexpected observation of tumor growth in two independent knockout mice models, we uncovered the novel function of PLD2 in CD8+ T cell proliferation." (PMID 29674728, 2018). "It is also plausible that PLD2 in some types of cells in tumor microenvironment is involved in inhibition of pro-angiogenic factor production/secretion." (PMID 29674728, 2018). "Taken together, these results suggest that PLD2 in CD8+ T cells plays a pivotal role in tumor growth suppression." (PMID 29674728, 2018). "Nevertheless, these results provide evidence that PLD2 in bone marrow-derived cells at least in part functions in anti-tumor immune responses." (PMID 29674728, 2018). "Tumor growth was significantly greater in the mice received Pld2−/− CD8+ T cells than in the mice received WT CD8+ T cells." (PMID 29674728, 2018). "If PLD2 negatively regulates the effector T cell-suppressive function of Treg cells, ablation of Pld2 from Treg cells would interfere with the anti-tumor immune response of CD8+ T cells." (PMID 29674728, 2018). "These lines of evidence are consistent with the notion that impaired CD8+ T cell infiltration into tumor microenvironment in Pld2−/− mice promotes tumor growth." (PMID 29674728, 2018).